EGFR (epidermal growth factor receptor)
Diseases named in the same sentence as EGFR in open-access papers (continued):
Sharing a sentence is not in itself a finding about the gene and the disease.
cancer (continued). "Because SPACE can penetrate skin and cells and EGF can target the EGFR overexpressed in cancer cells, SPACE-EGF is expected to carry siRNAs into B16 cells, which would then induce the apoptosis of B16 cells." (PMID 27374619, 2016). "EMT phenotype is also thought to be associated with resistance to targeted therapy in EGFR-driven NSCLC and in ALK-rearranged NSCLC treated with ALK TKIs as well as in K-Ras mutated cancers." (PMID 27119231, 2016). "With the wide variety of cancers displaying overexpression of wild type EGFR or its mutants, it is of little surprise that so much work has gone into development of a specific and potent anti-EGFR therapeutic." (PMID 27153091, 2016). "Of note, these EGFR-independent cancer cells demonstrated higher levels of basal autophagy than their parental cells and thrived under hypoxic, reduced-serum conditions in vitro." (PMID 30370422, 2016). "TNBC is sometimes classified into a “basal-type” cancer group, which is frequently defined by cytokeratin 5/6 and epidermal growth factor receptor (EGFR) positive staining." (PMID 27655695, 2016). "In this review, we will discuss data implicating FAM83 members in the aberrant activation of EGFR, MAPK, PI3K/AKT, and other cancer-associated signaling pathways and discuss their potential to serve as novel therapeutic targets." (PMID 27221039, 2016). "Taken together, these results suggest the role of EGFR in anti-cancer drug-resistance conferred by CAGE." (PMID 26863629, 2016). "This retrospective analysis summarizes the safety profile, efficacy and possible predictive factors of this anti-EGFR therapy in Chinese patients with advanced cancers." (PMID 27050148, 2016). "Overexpression of EGFR up to > 106 receptors per cell has been described for many cancer types, such as in the lung, head and neck, colon, pancreas, breast, ovary, bladder and kidney, and in gliomas." (PMID 26918608, 2016). "Early decrease in EGFR ctDNA indicates the presence of cancer cell populations that are sensitive to EGFR-TKIs." (PMID 27708242, 2016). "Same as cetuximab, nimotuzumab is another kind of recombinant humanized monoclonal immunoglobulin G1 antibody, with high binding specificity to the human extracellular EGFR, displaying high killing effect in the EGFR positive cancer cells." (PMID 26880889, 2016). "Combination chemotherapy of 5-FU and EGFR-TKI additively suppressed cancer cell survival in EGFR-mutant cell lines." (PMID 27268079, 2016). "Studies show that EGFR has high values in many types of cancer (oropharynx, oesophagus, stomach, colorectal, pancreas, non-small cell carcinoma of the lung, and SCC)." (PMID 27642215, 2016). "MiRNAs play important roles in the EGFR signaling pathway, therefore, they are remarkable for drug discovery in cancer therapy." (PMID 27790245, 2016). "With respect to clinical applications, we here report that effective inhibition of the EGFR-MEK-ERK pathway through combinatorial targeting does significantly prime the cytostatic RAS mutant cancer cells for apoptosis." (PMID 27845624, 2016). "This indicates that EGFR can be one of the key factors for cellular responses to SMF, especially for EGFR-expressing cancer cells." (PMID 27223425, 2016). "It was recently reported 56 that under normal development constitutive EGFR becomes inactivated as cancer stem cells differentiate and the current study supports this model." (PMID 26867148, 2016). "Similar molecular landscapes for the EGFR network are observed for each cancer type with RAS alterations most common in PAAD (86%), LUAD (39%), and COAD (50%) and PI3K alterations most common in LUSC (55%) and HNSCC (41%)." (PMID 27650546, 2016). "Our data suggest thatHNSCC with EGFR overexpression seems quite sensitive to the anti-cancer efficacy ofquercetin." (PMID 27510965, 2016). "Taken together, these results suggest that EGFR mediates anti-cancer drug-resistance conferred by CAGE through its effect on the interaction of EGFR with CAGE and HER2." (PMID 26863629, 2016).
cancer (continued). "Progress in understanding GC cancer biology has led to the development of treatment targeting the epidermal growth factor receptor (EGFR), human epidermal growth factor receptor-2 (HER-2), and angiogenesis, which has changed the therapeutic paradigm of GC." (PMID 27756337, 2016). "The responses of EGFR ctDNA to EGFR-TKI treatments provide an ideal model to investigate the role of ctDNA in monitoring cancer treatment." (PMID 27708242, 2016). "The expression of EGFR is highly regulated in normal cells, whereas some cancer cells have high constitutive levels of EGFR." (PMID 27256981, 2016). "Many research groups try to explain crosstalk between Notch and EGFR in order to understand the mechanism of this cooperation and to know how cancer cells use the Notch pathway to compensate for EGFR‐targeted inhibition." (PMID 27770511, 2016). "Many examples demonstrate excellent anti-cancer properties in preclinical development, and several EGFR-targeted immunotoxins have progressed to human trials." (PMID 27153091, 2016). "Among them, several genes were related in cancer pathway such as EGFR, RARA, FGF2, FGFR1, FGFR2, FGFR3, KIT, and CCND1." (PMID 27016420, 2016). "Logistically, it follows that tyrosine kinase receptors such as EGFR and others are promising candidate targets for cancer therapy and have led to the development of the tyrosine kinase inhibitors, such as the EGFR-targeting gefitinib and erlotinib." (PMID 27029067, 2016). "A low MIG6/EGFR ratio, predicting high EGFR activity, is highly correlated with erlotinib sensitivity in cancer cell lines derived from different tissues." (PMID 26788993, 2016). "The anti-cancer effect of kaempferol was mediated by inhibition of EGFR related Src, ERK1/2, and AKT pathways." (PMID 27175782, 2016). "TNF can induce the expression of transforming growth factor alpha (TGF α) and epidermal growth factor receptor (EGFR) in cancer cells." (PMID 27821804, 2016). "Since its discovery more than 20 years ago, the epidermal growth factor receptor (EGFR/HER1) has emerged as a key player in regulating cell proliferation and survival in different types of cancer." (PMID 27104520, 2016). "Of the four members in the family, EGFR and HER2 are well-established proto-oncogenes, and a number of cancer therapeutics targeting EGFR and HER2 are currently in clinical use." (PMID 27582551, 2016). "EGFR genomic DNA amplification leading to mRNA overexpression was often found in various types of human cancer." (PMID 26824984, 2016). "In this study, the EGFR was down-regulated in animals with high CLA-c9t11 content, result that agree with the association between CLA-c9t11 content and cancer prevention." (PMID 27875996, 2016). "Epidermal growth factor receptor (EGFR) is a transmembrane glycoprotein having tyrosine kinase activity that affects several critical signaling pathways related to cancer cell growth, apoptosis, angiogenesis, aggressiveness and invasiveness." (PMID 27833124, 2016). "In our study, intensive immunoreactivity of iNOS was detected in the cytoplasm of cancer cells, and EGFR and phosphorylated STAT3 were strongly expressed in cancer cells of NPC patients." (PMID 28050219, 2016). "It has recently been reported that p38 mitogen-activated protein kinase (MAPK) induces the phosphorylation of EGFR at Ser 1046/7, which results in its degradation in cancer cells." (PMID 27494858, 2016). "The EGFR signaling pathway is activated by binding of ligands, EGF, or TGF-α which is closely associated with cancer." (PMID 28053990, 2016). "EGFR and PI3K/AKT signalings have been implicated in tumorigenesis, invasion and metastasis of cancer including CRC." (PMID 27556502, 2016). "Epidermal growth factor receptor (EGFR) seems to be critical to cancer cell growth and proliferation, and the function of EGFR in these two settings appears to be different." (PMID 27565887, 2016).
cancer (continued). "Haem-mediated PGRMC1 dimerization is required for interactions with EGFR and cytochromes P450, cancer proliferation and chemoresistance against anti-cancer drugs; these events are attenuated by either CO or haem deprivation in cancer cells." (PMID 26988023, 2016). "Taken together, these results suggest that EGFR mediates anti-cancer drug-resistance conferred by CAGE." (PMID 26863629, 2016). "Comparing to chemotherapy as well as EGFR-TKIs, cancer vaccines are a relative new treatment strategy but show promise in NSCLC therapy." (PMID 27781159, 2016). "PRO is a known inhibitor of PAP, and has been shown to reduce the cell viability of EGFR-dependent cancer cell lines." (PMID 27899953, 2016). "Among the upregulated kinases in Treg, EGFR is known to be critically involved in tissue development and homeostasis but also in the pathogenesis of cancer which resulted in a widespread use of EGFR-targeted treatment in cancer patients in the past." (PMID 26881744, 2016). "Further study should consider and confirm EGFR as a marker and a therapeutic target for cardiac diseases, and even as a cross‐linker for cardiac diseases and cancer, especially EGFR‐positive cancer." (PMID 26762600, 2016). "Other mutations (such as non-T790M EGFR mutations D761Y, L747S and T854A, amplification of c-Met, loss of PTEN, PIK3CA mutations and BIM BH3 deletion) have been reported to result in the resistance to EGFR TKIs in some cancers." (PMID 26909593, 2016). "Suppression of NAG-1 expression using its shRNA led to a significant inhibition of EGFR expression and its downstream signaling mediator ERK1/2, indicating the positive regulation of cancer EGFR-linked signals by NAG-1." (PMID 27708225, 2016). "Shed EGFR ectodomain (sEGFR), which is present in cancer patient sera, can potentially bind tracer and therefore influence tracer kinetics." (PMID 27602494, 2016). "Various biomarkers predictive for anti-EGFR inhibitor efficacy have been explored for different cancer types." (PMID 27136744, 2016). "In this study, we survey the genomic landscape of the EGFR network among cancers in which EGFR inhibitors are often effective." (PMID 27650546, 2016). "AKT1 and AKT2 are frequently activated in human cancer following loss of the lipid phosphatase PTEN, activating mutations and/or copy number variation in EGFR or HER2 tyrosine kinase receptors, activating mutations in KRAS, in PIK3CA or in AKT1 itself." (PMID 26859676, 2016). "The EGFR is an attractive host therapeutic target for infectious disease as EGFR inhibitors have been FDA-approved as cancer treatments and their clinical use is well documented." (PMID 27414801, 2016). "EMT has been shown to be important on conferring drug resistance characteristics to cancer cells against conventional therapeutics including taxol, vincristine, oxaliplatin, or epidermal growth factor receptor (EGFR) targeted therapy." (PMID 27279541, 2016). "It has also been shown that EGF activation of EGFR further accentuates CDCP1-induced pro-cancer effects by inhibiting proteasome-mediated, palmitoylation-dependent constitutive degradation of CDCP1." (PMID 26973855, 2016). "We showed that haem-mediated dimerization of PGRMC1 enhances proliferation and chemoresistance of cancer cells through binding to and regulating EGFR and cytochromes P450." (PMID 26988023, 2016). "The significant discovery of a new family of oncogenes as critical mediators of EGFR/RAS signaling provides the basis for the development of novel therapeutics that target FAM83 members in a wide variety of cancers." (PMID 27221039, 2016). "It has been shown that lipophilic nitro-benzoxadiazole (NBD) compounds rapidly move across the plasma membrane and enhance Epidermal Growth Factor Receptor (EGFR) tyrosine phosphorylation in cancer cells." (PMID 26883293, 2016). "Among these, selected miRNAs, miR-146a, targeting EGFR, is differentially expressed in various cancer histologies." (PMID 26919248, 2016).
cancer (continued). "We performed clinical cancer gene test of patient tissue samples which were obtained before treatment with EGFR TKIs in order to identify genetic alterations that confer primary resistance to EGFR TKIs." (PMID 27121209, 2016). "When the NSCLCs are exposed to EGFR inhibitors, these pathways are turned off and cancer cells undergo apoptosis." (PMID 26916442, 2016). "The EGFR signaling pathway plays a critical role in colonic tumorigenesis and is a target of many cancer therapies." (PMID 27683110, 2016). "Both ligand- and stress-induced endocytosis and degradation of EGFR have been observed in cancer cells." (PMID 27034618, 2016). "We propose that stress conditions down-regulate cell surface EGFR in cancer cells by the two coordinated but independent processes, i.e., the p38-mediated endocytosis and the Caspase-3-catalyzed degradation of EGFR, to impede cancer cell proliferation." (PMID 27034618, 2016). "The use of antibodies is an established cancer therapy approach, with antibodies targeting EGFR, ERBB2, and VEGF (vascular endothelial growth factor) demonstrating effectiveness." (PMID 26760963, 2016). "Cancer cells in MPE had coexisting acquired PIK3CA c.1633G > A (p.E545K) mutation and EGFR c.2369C > T (p.T790M), in addition to EGFR c.2573T > G (p.L858R)." (PMID 27734950, 2016). "The Epidermal Growth Factor Receptor (EGFR) and its mutations contribute in various ways to tumorigenesis and biology of human cancers." (PMID 27153109, 2016). "From cancer biology it is known that EGFR and Ezrin form a functional complex, however, their exact interactions are still elusive." (PMID 26881744, 2016). "Anti-EGFR antibodies have been under investigation for treatment of various EGFR-expressing cancers for several decades, with varying degrees of success." (PMID 27153091, 2016). "Cetuximab is an antibody that specifically blocks epidermal growth factor receptor (EGFR) oncogenic signaling in cancer cells." (PMID 27286453, 2016). "Reportedly, taxol increases the phosphorylation of EGFR, suggesting the role of EGFR in the response to anti-cancer drugs." (PMID 26863629, 2016). "In parallel, targeted therapies now take a major place in anti-cancer treatment, particularly in HNSCC where Epidermal Growth Factor Receptor (EGFR)'s overexpression, is associated with a poor prognosis." (PMID 27374096, 2016). "This is why, co-targeting EGFR-signaling and autophagy is now emerging as a prudent approach in inhibiting cancer cell growth compared to the targeting of only one axis." (PMID 30370422, 2016). "As there are numerous resistance mechanisms to EGFR TKIs, many of which remain unexplained even in common cancers 22, it was beyond the scope of this project to pursue this further." (PMID 27102572, 2016). "The EGFR pathway contributes in many ways to cancer proliferation and angiogenesis to many types of cancer." (PMID 27834913, 2016). "Nuclear factor-kappaB (NF-κB) has been identified as an important regulator of cancer cell invasion, metastasis and angiogenesis and is a downstream target of EGFR." (PMID 27886147, 2016). "The epidermal growth factor receptor (EGFR) is an oncogenic protein linked to poor prognosis in pancreatic (and other) cancers that illustrates how hypersialylation can deter cancer progression." (PMID 27613843, 2016). "And, it is hard to obtain cancer tissues to detect relevant signaling pathway by immunohistochemistry (IHC) during the process of EGFR-TKI treatment." (PMID 27655708, 2016). "Increased mRNA expression levels of EGFR were observed in various cancers such as head and neck, ovary, cervix, bladder, oesophagus, stomach, brain, breast, endometrium, colon and lung, and frequently conferred an adverse prognosis." (PMID 26824984, 2016).
cancer (continued). "Most data supporting the cancer-relevance demonstrate the existence of transactivation of EGFR in various cancer cell lines in the lab." (PMID 26771606, 2016). "Alternatively, there is evidence that the stability of AGO2 in the RISC is enhanced by EGFR/ERBB1 through MAPK signaling in cancer cell line MDA-MB-231." (PMID 27701455, 2016). "Cetuximab, an EGFR neutralizing monoclonal antibody, is used to treat certain cancers, particularly colon cancer." (PMID 27635238, 2016). "Cancer treatments based on blocking EGFR signaling are emerging as promising alternatives; however, tyrosine kinase inhibitors (TKIs) show only modest effects on most cancer types." (PMID 27487128, 2016). "A number of small‐molecule specific inhibitors of EGFR have been developed for cancer treatment and more than six inhibitors have been used in clinical." (PMID 26762600, 2016). "Because EGFR is known to play a role in epithelial tumor biology, various EGFR-targeted cancer therapies are currently being developed." (PMID 27438047, 2016). "A notable example is EGFR; in highly proliferating cells, including cancer cells, it is translocated to the nucleus, where it can activate transcription of genes involved in cell proliferation." (PMID 27911862, 2016). "Patients with EGFR-mutated NSCLC have shown clinical responses to the orally administered EGFR inhibitor gefitinib, leading to a new era of the targeted therapy of human cancer." (PMID 27223277, 2016). "Encouraging outcome from these studies supported clinical efficacy of EGFR for anti-cancer therapy and led to the development of EGFR-targeting antibodies like cetuximab or panitumumab and TKIs like gefitinib, erlotinib, and lapatinib." (PMID 30370422, 2016). "Inhibition of EGFR signaling has also been shown to decrease the production of VEGFA in cancer cells." (PMID 27941682, 2016). "EGFR function is frequently dysregulated in epithelial tumours, and EGFR signalling has been shown to play an important role both in cancer progression and in EMT-like transitions." (PMID 27711186, 2016). "Both fc-rPEI-Cdots/cyclin B1+ EGFR and fc-rPEI-Cdots/cyclin B1 complexes showed anti-cancer effect in treatment period for 72 hrs." (PMID 26880047, 2016). "Imetelstat in combination with or following erlotinib treatment in EGFR mutant cancers would be predicted to work concomitantly by treating the EGFR mutant cancer cells with erlotinib while concurrently shortening telomeres." (PMID 27192120, 2016). "ZNF32 overexpression enhanced the tolerance of cancer cells to not only the conventional anti-proliferative drug CIS but also the EGFR inhibitor GEF." (PMID 27763636, 2016). "EGFR is overexpressed in many aggressive cancers, and previous study indicates that p85α can be activated by transmembrane tyrosine kinase receptors, such as EGFR, HER2 and IGF1-R." (PMID 26918608, 2016). "Epidermal growth factor receptor has long been proposed as an attractive and promising target for anti‐cancer treatment." (PMID 27241841, 2016). "In GBM cells, EGFR activation promote cancer cell growth and survival, inhibition of EGFR slows cell migration." (PMID 27167112, 2016). "EGFR is a member of human EGF receptor (HER) family of tyrosine kinases whose dysregulated signaling is involved in many cancers of epithelial origin, accounting for 80% of all solid tumors." (PMID 27806094, 2016). "With the development of molecular-targeted therapy, epidermal growth factor receptor (EGFR) represents a promising new therapeutic target in various cancers." (PMID 27313893, 2016). "Epidermal growth factor receptor (EGFR) signalling plays a central role in many cancer types and is a major drug target." (PMID 27899953, 2016). "A pathway-centric view highlighted the number of interactions between CFEs in cancer pathways (EGFR, ERK-MAPK, PI3K-MTOR, and DNA repair and cell-cycle-related pathways) and drugs targeting those CFEs." (PMID 27397505, 2016).